ADNP (activity dependent neuroprotector homeobox)
Diseases named in the same sentence as ADNP in open-access papers (continued):
Sharing a sentence is not in itself a finding about the gene and the disease.
ovarian carcinoma (6 papers, 2019 to 2024). A malignant neoplasm originating from the surface ovarian epithelium. "Among them, ADNP is usually up-regulated in most cancers such as ovarian cancer and colorectal cancer." (PMID 33663517, 2021). "Consistent with our observations, DNA amplification and overexpression of the transcription factor ADNP were identified in high-grade and poorly prognostic ovarian cancer." (PMID 33240802, 2020). "To confirm the essential role of ADNP in ovarian cancer proliferation, we next identified HGSOC cell lines that are characterized by high ADNP protein expression; OVCAR5 and OVCAR3 were selected for further in vitro experiments." (PMID 31767542, 2019). "Thus, we next validated the impact of shRNA mediated silencing of ADNP on the expression of a subset of these cell cycle genes in ovarian cancer cell lines." (PMID 31767542, 2019). "Although the exact mechanisms by which ADNP modulates ovarian cancer tumorigenesis remains to be determined, our data, in combination with previous studies, demonstrate that ADNP mediates its effects on HGSOC tumorigenesis, in part, by promoting dysregulation of cell cycle checkpoints." (PMID 31767542, 2019). "Importantly, we validated that ADNP mediates cell proliferation through dysregulation of cell cycle checkpoints in ovarian cancer." (PMID 31767542, 2019). "While ADNP has not been extensively studied in cancer, or in ovarian cancer specifically, it is localized to chromosome 20q12, a region that is frequently amplified in many malignancies including HGSOC, breast, pancreatic, and colon cancers." (PMID 31767542, 2019).
colorectal cancer (5 papers, 2019 to 2024). A primary or metastatic malignant neoplasm that affects the colon or rectum. "ADNP is also part of a protein hub that is enriched in the signal transduction of pathways involved in colorectal cancer." (PMID 36945042, 2023).
colon cancer (4 papers, 2019 to 2024). "The role of ADNP in tumorigenesis has recently gained profound research attention, and ADNP is closely linked with tumor growth, particularly in various cancers, including breast, ovarian, pancreatic, and colon cancer." (PMID 33240802, 2020). "However, a recent study suggested that negative ADNP expression in the colon activates the WNT signaling pathway, promoting colon cancer cell migration, invasion, and proliferation." (PMID 33240802, 2020).
congenital heart disease (3 papers, 2023 to 2025). A heart disease that is present at birth. "Apart from such frequent condition, a large minority of individuals with an ADNP mutations also suffered from congenital heart disease, ear–nose–throat system dysfunction, short stature, and abnormalities of the endocrine system." (PMID 36945042, 2023).
sarcoma (3 papers, 2019 to 2023). A usually aggressive malignant neoplasm of the soft tissue or bone. "Consistent with our research, a number of studies have reported that ADNP plays an important role in regulating cell growth, proliferation in some types of sarcomas and neuronal tissue as well as modulating AKT signaling pathway." (PMID 33240802, 2020). "ADNP expression in GBM (r = -0.53), sarcoma (SARC) (r = -0.52), WT (r = -0.63) was most negatively related to immune score, and expression in GBM (r = -0.52), WT (r = -0.58), NBL (r = -0.47) was most negatively related to estimated score." (PMID 37525242, 2023).
Anxiety (2 papers, 2024 to 2025). Intense feelings of nervousness, tension, or panic often arise in response to interpersonal stresses. "Mutations of ADNP and SHANK3 impair the binding of ADNP and Shank3 to actin leading to autistic behaviors, anxiety, and depression due to synaptic dysfunctions." (PMID 39223276, 2025).
asthma (2 papers, 2023 to 2025). "Analysis of enriched KEGG pathways revealed that ADNP target genes included those associated with Th2 cell differentiation, JAK-STAT, and T cell receptor signaling, and asthma-related pathways." (PMID 37285842, 2023). "Kyoto Encyclopedia of Genes and Genomes (KEGG) pathway analysis indicated that the differentially expressed genes (DEGs) downregulated in the absence of ADNP were associated with “Asthma” pathways, which correlates with the roles of IL-13 and Th2 cells in allergic asthma." (PMID 37285842, 2023). "Although ADNP has not been identified as a common factor in asthma susceptibility, unlike IL-4, IL-5, and IL-13, it was reported among a subset of genes that were differentially expressed by CD4+ lymphocytes and that predicted more atopic from less atopic children." (PMID 37285842, 2023).
bladder tumor (2 papers, 2020 to 2021). "Cox regression analysis also showed that ADNP was a risk prognostic factor for bladder tumor-progression after chemotherapy." (PMID 34335928, 2021). "Similarly, western blot analysis revealed that ADNP protein expression in human primary bladder tumor was also significantly upregulated." (PMID 33240802, 2020).
frontotemporal dementia (2 papers, 2014 to 2020). Frontotemporal dementia (FTD) comprises a group of neurodegenerative disorders, characterized by progressive changes in behavior, executive dysfunction and language impairment, as a result of degeneration of the medial prefrontal and frontoinsular cortices. "For example, our previous data showed a reduction in brain ADNP expression in aging animals, exhibiting microtubule-tau pathology (a mouse model for frontotemporal dementia), and a positive correlation between ADNP serum concentrations and IQ test performance in elderly individuals." (PMID 33086621, 2020).
hepatocellular carcinoma (2 papers, 2023 to 2024). A malignant tumor that arises from hepatocytes. "Since the varied roles of ADNP were still controversial in the tumorigenesis and progression of multiple cancers, it was meaningful to further investigate the potential mechanism ADNP involved in hepatocellular carcinoma (HCC)." (PMID 37525242, 2023).
microcephaly (2 papers, 2022 to 2025). A congenital or acquired developmental disorder in which the circumference of the head is smaller than normal for the person's age and sex. "Specifically, patient UniPD_0129 with a frameshift variant in ADNP presented with macrocrania, despite the gene being primarily associated with skull anomalies such as plagiocephaly, trigonocephaly, and, less frequently, microcephaly." (PMID 40019509, 2025).
multiple sclerosis (2 papers, 2012 to 2020). A progressive autoimmune disorder affecting the central nervous system resulting in demyelination. "Other findings associated reduced ADNP expression to the progression of multiple sclerosis and increased pro-inflammatory markers, and potential modulation by the ADNP derived drug candidate davunetide (NAP)." (PMID 23162535, 2012). "While VIP may present a dual function in the regulation of multiple sclerosis, it should be borne in mind that ADNP regulation, while in part associated with VIP and PACAP, is regulated by other control mechanisms." (PMID 23162535, 2012). "An independent follow-up study assessed the expression of ADNP in the immune system of healthy subjects and multiple sclerosis patients." (PMID 32072336, 2020). "Furthermore, ADNP mRNA in peripheral blood mononuclear cells was reduced in multiple sclerosis patients compared to controls." (PMID 32072336, 2020).
muscle disorders (2 papers, 2020 to 2025). "To further understand the differential involvement of ADNP in the various muscle disorders, we have also assessed the levels of the ADNP binding proteins EB1 (MAPRE1) and EB3 (MAPRE3)." (PMID 33086621, 2020).
serous ovarian cancer (2 papers, 2019 to 2020). "Moreover, ADNP was identified to be an oncogenic mediator of cell proliferation through dysregulation of cell cycle checkpoints in high-grade serous ovarian cancer." (PMID 33240802, 2020).
anal stenosis (1 paper, 2018). "However, without obesity and short stature at age of diagnosis, patients ASD-821 harboring a de novo LOF mutation (start lost) in ADNP presented novel phenotype of micropenis and anal stenosis." (PMID 30555518, 2018).
Angelman syndrome (1 paper, 2017). A neurogenetic disorder characterized by severe intellectual deficit and distinct facial dysmorphic features. "Our String analysis puts the ubiquitin system (UBC) in a central point for ADNP regulatory pathways, and in that respect, Angelman syndrome is caused by ubiquitin protein ligase E3A mutations." (PMID 28221363, 2017).
B cell lymphoma (1 paper, 2023). "Moreover, ADNP knockdown in GCB subtypes of B cell lymphoma inhibited proliferation, overall suggesting that epigenetic super-enhancer-mediated control of ADNP contributes to GCB-DLBCL progression." (PMID 36945042, 2023).
bladder urothelial carcinoma (1 paper, 2020). "We examined the relationship between ADNP and the clinicopathological characteristics of bladder urothelial carcinoma." (PMID 33240802, 2020).
cocaine abuse (1 paper, 2024). Disorders related or resulting from use of cocaine. "Our results implicate ADNP in cocaine abuse, further placing the ADNP gene as a key regulator in neuropsychiatric disorders." (PMID 39251453, 2024).
cocaine addiction (1 paper, 2024). "In conclusion, our findings suggest that ADNP is a potential novel biomarker and regulator of cocaine addiction, at the synaptic level." (PMID 39251453, 2024). "Finally, we review possible mechanisms through which ADNP might mediate cocaine-response and conclude by discussing implications of the role of ADNP/NAP in cocaine addiction for future prevention and treatment." (PMID 39251453, 2024).
cocaine use disorder (1 paper, 2024). A substance-related disorder that involves the recurring use of cocaine despite negative consequences. "Recently, we presented ADNP as an alcohol-responsive gene and negative regulator of alcohol consumption in adult female mice, and the question arises whether ADNP is also involved in cocaine use disorder." (PMID 39251453, 2024).
dementia (1 paper, 2022). Loss of intellectual abilities interfering with an individual's social and occupational functions. "In conclusion, this study shows for the first time that the comparison between full-length and truncated form levels of DYRK1A coupled with ADNP levels could be used in trials targeting pathophysiological mechanisms of dementia in individuals with DS." (PMID 35740400, 2022). "Our results show that the comparison between full-length and truncated-form levels of DYRK1A coupled with ADNP levels could be used in trials targeting pathophysiological mechanisms of dementia in individuals with DS." (PMID 35740400, 2022).
diffuse large B-cell lymphoma (1 paper, 2023). "ADNP expression also had a remarkable connection with MSI in lymphoid neoplasm diffuse large B cell lymphoma (DCLBCL), COAD, COADREAD, HNSC, PRAD, THCA, STES, BRAC, lung squamous cell carcinoma (LUSC), LUAD." (PMID 37525242, 2023).
ductal carcinomas (1 paper, 2007). "Majority of genes with this function were upregulated in ductal carcinomas such as AHCTF1, IRAK1, NRIP1, ADNP." (PMID 17389037, 2007).
intestinal cancer (1 paper, 2022).
Kleefstra syndrome (1 paper, 2025). A genetic disorder characterized by intellectual disability, childhood hypotonia, severe expressive speech delay and a distinctive facial appearance with a spectrum of additional clinical features.
lupus (1 paper, 2017). "In addition, in a mouse model that simulates lupus progression, animals experienced an increased expression of MAP17 connected with a decrease in RFX3, a negative regulator of HLAs, and decreases in HERC2 and ADNP." (PMID 29228712, 2017).
Lynch syndrome (1 paper, 2024). An autosomal dominant hereditary neoplastic syndrome characterized by the development of colorectal carcinoma and a high risk of developing endometrial carcinoma, gastric carcinoma, ovarian carcinoma, renal pelvis carcinoma, and small intestinal carcinoma. "The gene ontologies for list 7- linked CHTOP, ADNP, HLTF, WAPL, ZMYM4, and ZNF146 to Lynch Syndrome." (PMID 39480826, 2024). "We propose that ADNP, CHTOP, HLTF, MTF2, WAPL, and ZMYM4 are novel genes in Lynch Syndrome." (PMID 39480826, 2024).
Neurodegeneration (1 paper, 2019). Progressive loss of neural cells and tissue. "It has been reported that, at an early stage of the pathological alteration in the neurodegeneration disease of humans, the downregulation of protein ADNP expression is observed." (PMID 31749588, 2019).
Neurodevelopmental delay (1 paper, 2024). "Importantly, epigenome-wide analysis of the ADNP cerebellum identified CpG methylation differences and expression of multiple pathways causing neurodevelopmental delay." (PMID 38637827, 2024).
post-traumatic stress disorder (1 paper, 2024). An anxiety disorder precipitated by an experience of intense fear or horror while exposed to a traumatic (especially life-threatening) event. "ADNP is notably associated with ASD and developmental delay (DD), while the ADNP2 gene is closely linked with SZ, post-traumatic stress disorder (PTSD), ASD, and DD." (PMID 39273418, 2024).
substance abuse (1 paper, 2024). The use of a drug for a reason other than which it was intended or in a manner or in quantities other than directed. "Taken together, current data support the role of ADNP in mediating substance abuse in a drug- and sex-dependent manner." (PMID 39251453, 2024).
cancer (14 papers, 2011 to 2025). A tumor composed of atypical neoplastic, often pleomorphic cells that invade other tissues. "On a structural point of view, cancer-causing ADNP mutations seem distributed all over the protein in the primary structure, but they are close to each other at the tertiary structure." (PMID 36945042, 2023). "In this study, we found the expression of ADNP was promoted in most cancers and associated with poor prognosis in LGG, HCC, LAML, READ, and BRCA." (PMID 37525242, 2023). "The discovery of ADNP mutations in neurological disorders ignited an interest to explore the role of ADNP in cancer." (PMID 34335928, 2021). "More recent studies from the TCGA pan-cancer project reported that while ADNP is rarely mutated in these tumours, it is part of a subnetwork which includes members of the SWI/SNF complex that have been shown to contribute to tumorigenesis." (PMID 31767542, 2019). "The correlation between ADNP and prognosis, immune cell infiltration, immune checkpoints, chemokines, tumor mutation burden, microsatellite instability, and genomic mutation of pan-cancer cohorts in The Cancer Genome Atlas was analyzed." (PMID 37525242, 2023). "Similarly to high prevalence of mutations in genes encoding subunits of the SWI/SNF chromatin remodeling complexes or other epigenetic regulators in cancer development, increasing evidence also points to an oncogenic role for ADNP mutations." (PMID 36945042, 2023). "Cancer-specific missense mutation A1866D in CHD4 C-terminus domain causes a reduction of CHD4 interaction with ADNP, suggesting that ChAHP formation might be perturbed in cancer cells." (PMID 36945042, 2023). "To further discuss the underlying impact of ADNP expression on carcinoma progression and metastasis, we detected the ADNP expression levels in different pathological stages and observed a statistically significant difference in HCC, adrenocortical carcinoma (ACC), and OV." (PMID 37525242, 2023). "Studies have shown that under different stress conditions, ADNP may mutate or differ in expression, thus accelerating the progression of cancer." (PMID 34335928, 2021). "In our research, we exhibited the correlation between CD8 + T cells, macrophages, CAFs, Tregs, endothelial cells, MDSCs and ADNP expression in various cancers of TCGA with a heat map." (PMID 37525242, 2023). "NDD-causing mutations affecting protein structure are overrepresented near the ADNP homeobox domain, suggesting that both cancer and neurodevelopment entail the disruption of ADNP chromatin-binding activity." (PMID 36945042, 2023). "ADNP was upregulated in most cancers and patients with elevated ADNP expression were related to poor survival in several types of cancers including HCC." (PMID 37525242, 2023). "We observed ADNP expression had the most noteworthy positive correlation with the infiltration of CAFs, endothelial cells, and MDSCs in the majority of pan-cancers." (PMID 37525242, 2023). "Overall, there is increasing consensus that ADNP contributes to tumorigenesis and cancer progression." (PMID 36945042, 2023). "Since ADNP was regarded as having a crucial cancer-promoting role in diverse kinds of tumors, its specific function in HCC remains unidentified." (PMID 37525242, 2023). "In this study, we explored the expression and prognostic value of ADNP across cancers and first reported that ADNP participated in the proliferation, invasion, migration, immune evasion, and radioresistance in HCC." (PMID 37525242, 2023). "We further studied the connection between ADNP expression and immune score, stromal score, and estimated score in pan-cancers using sanger-box." (PMID 37525242, 2023). "Activity-dependent neuroprotective protein (ADNP) was originally cloned from mouse carcinoma cells, differentiated into neuroglial cells." (PMID 21267468, 2011).